BMAL1 (basic helix-loop-helix ARNT like 1)
Diseases named in the same sentence as BMAL1 in open-access papers (continued):
Sharing a sentence is not in itself a finding about the gene and the disease.
colitis (continued). "Overall, these data suggest the expression of stem cell and precursor cell markers is reduced in Bmal1-/- mutants at all stages pre- and post-colitis." (PMID 35223537, 2022). "Histological analyses indicate worsened colitis severity in Bmal1-/- mutant colon, and colon infiltration of immune system cells shows a daily rhythm that is lost in the Bmal1-/- mutant." (PMID 35223537, 2022). "It is thus likely that in Bmal1-/- mutant mice, where these processes are disrupted, the microbiome contributes to colitis severity." (PMID 35223537, 2022). "We also examined the effects of Bmal1 knockout (i.e., genetic disruption of circadian clock) on colitis development." (PMID 30315268, 2018). "Targeting BMAL1 and inhibition of apoptosis may provide a potential strategy for prevention and treatment of colitis." (PMID 40307620, 2025). "Moreover, reducing Bmal1 expression by SR9009 at ZT0 had the best efficacy in alleviating DSS-induced colitis." (PMID 40307620, 2025). "Indeed, it was found that BMAL1 exacerbates colitis severity by hindering healing and affecting the activity of the Wnt and Hippo pathways during regeneration." (PMID 40613788, 2025). "Used intestinal epithelial-specific Bmal1 knockout mice challenged with DSS to induce colitis." (PMID 41425940, 2025). "Mice lacking Rorα or Bmal1-driven Lnc-UC (a long noncoding RNA that is associated with colitis, particularly by reducing Rev-erbα expression) are more likely to have colitis than the control group." (PMID 38089624, 2023). "Indeed, recent findings have shown that Bmal1 functions in macrophages and B-cells during colitis to resolve inflammation." (PMID 35223537, 2022). "Thus, we investigated the pro-inflammatory cytokine expression in Bmal1+/+ control and Bmal1-/- mutant colon tissue following DSS-colitis." (PMID 35223537, 2022). "The role of clock genes as immuno-regulators of colitis is supported by three recent studies, as well as our present work where we demonstrate increased inflammation during resting periods in Bmal1-/- mutant mice." (PMID 35223537, 2022). "We observed significantly increased severity of DSS-colitis in Bmal1-/- mutant mice." (PMID 35223537, 2022). "Loss of Bmal1 also reduces the expression of AMPs, and increases inflammation, suggesting that certain aspects of the colitis response is absent." (PMID 35223537, 2022). "An increase in lesions is apparent in Bmal1-/- colon tissue, who cannot resolve colitis." (PMID 35223537, 2022). "Similar to jet lag, Bmal1 ablation sensitized mice to DSS-induced colitis." (PMID 30315268, 2018). "Interestingly, the decreased BMAL1 expression in UC patients was consistent with the observation in DSS-induced colitis in mice in which Bmal1 levels were gradually declined at different time points during the colitis progress (Fig. EV6C)." (PMID 40307620, 2025). "However, to date, no studies have associated Bmal1 with autophagy in colitis and intestinal barrier function." (PMID 38895112, 2024). "Furthermore, we observed decreased expression of Bmal1 in the colon of mice with DSS-induced colitis, which is consistent with previous studies, suggesting that Bmal1 may be a key factor in the process of CRD affecting UC pathogenesis." (PMID 38895112, 2024). "Mice lacking Rorα or Bmal1-driven Lnc-UC were more susceptible to colitis than their control group." (PMID 37218867, 2023). "As DSS-induced colitis and cell apoptosis exhibited a Bmal1-dependent circadian rhythm pattern, we investigated the optimal timing of SR9009 administration in colitis treatment." (PMID 40307620, 2025). "Therefore, Bmal1 depletion may exert a protective role in colitis by attenuating cell apoptosis." (PMID 40307620, 2025). "Notably, Bmal1 displayed its peak expression at the early resting time-point (ZT0) and reached its minimum at the early active time-point (ZT12), indicating that the dynamic expression of Bmal1 might be involved in the resistance to colitis in the active phase." (PMID 40307620, 2025).
colitis (continued). "To investigate the functional relevance of the intestinal clock in intestinal inflammation, we generated intestinal epithelium-specific Bmal1 knockout mice and examined its effect on dextran sodium sulfate (DSS)-induced colitis." (PMID 40307620, 2025). "To further test this, we probed the same cohort of Bmal1+/+ control and Bmal1-/- mutant mice for immune system blood cells (marked by anti-CD45) which infiltrate tissue lesions during DSS-induced colitis." (PMID 35223537, 2022). "Despite this finding, given the significant impact of IEC-specific Bmal1 deletion on the rhythmic microbiome and colonic transcriptome in our naive mice, it is somewhat surprising that responses to our DSS induced colitis model were comparable to wildtype littermates." (PMID 40822350, 2025). "More recently, mice lacking Bmal1 in IECs have demonstrated protection against DSS colitis, with authors identifying a reduction in apoptosis as the potential mechanism." (PMID 40822350, 2025). "A lack of the intestinal clock gene (Bmal1) in intestinal epithelial cells (IECs) in a chemically and a novel genetically induced colitis model (DSS, Bmal1IEC−/−xIL-10−/−) promoted colitis and dramatically reduced survival rates." (PMID 38918576, 2024). "Our study found that Bmal1 expression was decreased in the colon of CRD mice, and downregulation of Bmal1 expression due to CRD or Bmal1 knockout lead to more severe colitis, as evidenced by more severe impairment of intestinal barrier function and more apoptosis IECs." (PMID 38895112, 2024). "This study suggests that CRD leads to the downregulation of Bmal1 expression in the colon, which may exacerbate DSS-induced colitis in mice, and that Bmal1 may serve as a novel target for treating inflammatory bowel disease." (PMID 38895112, 2024). "Furthermore, the circadian rhythm of regeneration in Bmal1-/- mutant mice is disrupted and reduced during recovery from DSS-induced colitis, with a concomitant reduction in cell proliferation." (PMID 38895112, 2024). "At this stage of recovery, Bmal1+/+ controls no longer have any DSS-induced lesions present (colitis is resolved), but Hopx and Lgr5 expression persists in the Bmal1-/- mutant lesions." (PMID 35223537, 2022). "Using a mouse model of circadian disruption via Bmal1, we have shown that the absence of circadian rhythms leads to more severe colitis, a form of IBD." (PMID 35223537, 2022). "We observed a drastic decrease in the recovery of Bmal1-/- mutant mice, indeed nearly all Bmal1-/- mutants are not able to tolerate colitis and had to be euthanized much earlier than controls." (PMID 35223537, 2022). "IEC-specific Bmal1 deletion did not impact the acute DSS colitis phenotype." (PMID 40822350, 2025). "IEC-specific Bmal1 deletion did not impact colitis severity." (PMID 40822350, 2025). "A loss of rhythmic oscillations in Breg cells in intestinal epithelial lymphocytes, a reduction in the number of Breg+ PDL1+ cells, and dysfunction of CD4+ T cells in mice lacking the core biological clock gene Bmal1 promote DSS-induced colitis and IBD-related colorectal cancer in mice." (PMID 38895112, 2024). "In addition, UA pre-treatment by oral administration to female C57BL/6 mice showed the improvement in the fecal IgA concentrations, tight junction expression (Clnd1 and Clnd4), and clock gene expression (Bmal1 and Per2) in a DSS-induced colitis model induced using DSS treatment." (PMID 39064706, 2024). "Like colitis symptoms, these rhythms are not present in Bmal1-/- mutant mice." (PMID 35223537, 2022). "Indeed, Bmal1 mutant mice carry a greater burden of ulcers/lesions throughout the colon, and these do not resolve after colitis whereas those of controls are completely healed." (PMID 35223537, 2022).
Cognitive impairment (16 papers, 2015 to 2025). Abnormal cognition is characterized by deficits in thinking, reasoning, or remembering. "Targeting the 5-HT2C receptor may offer a potential therapeutic strategy for mitigating cognitive impairments associated with BMAL1 dysfunction." (PMID 39611170, 2024). "Mice with a conventional targeted deletion of the essential circadian clock gene Bmal1 (Bmal1-/-) show not only a loss of circadian rhythms and an impairment of light entrainment, but also other severe impairments, including premature aging and cognitive deficits." (PMID 32092990, 2020). "Consistent with the administration route of intraperitoneal injection, direct application of CCPA in the hippocampus (by a mini‐osmotic pump) ameliorated, whereas DPCPX treatment aggravated, the cognitive impairments in Bmal1‐iKO mice." (PMID 40539410, 2025). "Manipulations of intestinal BMAL1 by both methods result in cognitive impairments, solidifying the contribution of intestinal BMAL1 to cognitive function." (PMID 40539410, 2025). "CCPA (2‐chloro‐N6‐cyclopentyladenosine, a specific agonist of A1R) treatment (0.05 mg kg−1, i.p.)ameliorated cognitive deficits with respect to memory in Bmal1‐iKO mice." (PMID 40539410, 2025). "In young (6–8-week-old) BMAL1-KO mice, disruption of this process leads to cognitive impairment via dysregulation of synaptic neurotransmission." (PMID 41440117, 2025). "Propofol treatment attenuates acute SD‐induced cognitive impairment and sleep structural disturbance by upregulating BMAL1 expression." (PMID 39015099, 2024). "Melatonin upregulates BMAL1 to attenuate chronic sleep deprivation‐related cognitive impairment by alleviating oxidative stress." (PMID 36563187, 2023). "The stressed behaviors seen in BMAL1-KO monkeys, such as the head being buried in the hands, avoiding care personnel and schizophrenia-related cognitive impairment in auditory oddball MMN trials, are rather unique among animal models." (PMID 34691834, 2019). "Mice with targeted deletion of the clock gene Bmal1 (Bmal1‐/‐) show disrupted regulation of reactive oxygen species homeostasis, accelerated aging, neurodegeneration and cognitive deficits." (PMID 26142744, 2015). "Thus, there is a noticeable relationship between the metabolic function of astrocytic BMAL1, its role in the activation of astrocytes and astrocytic apoptosis, and cognitive impairment, which is a predictor of neurodegeneration." (PMID 41440117, 2025). "We further tested whether enhancement of adenosine signaling by an A1R agonist can attenuate Bmal1‐iKO‐induced cognitive impairments." (PMID 40539410, 2025). "We speculated that melatonin upregulated BMAL1 to attenuate chronic sleep deprivation related cognitive impairment by allevaiting oxidative stress." (PMID 36563187, 2023). "Collectively, we speculated that melatonin upregulated BMAL1 to attenuate chronic sleep deprivation‐related cognitive impairment by alleviating oxidative stress." (PMID 36563187, 2023). "Together, these findings indicate that agents that target the molecular clock-Bmal1 in microglial cells might be developed as a novel means to treat both metabolic and cognitive disorders." (PMID 34050326, 2021). "Given that cognitive impairment in Bmal1‐iKO mice is attributed to a reduced adenosine tone and compromised hippocampal adenosine signaling, we wondered whether enhancement of adenosine signaling by adenosine supplementation can rescue the cognitive deficits in the knockouts." (PMID 40539410, 2025). "Hence, our results validate the functional role of Bmal1 in fear learning and memory and suggest that Bmal1 dysfunction may contribute to cognitive impairments in psychiatric and neurodegenerative disorders." (PMID 39611170, 2024). "Furthermore, Bmal1 knockdown affects astrocyte morphology, impairing synaptic coverage and neurotransmission, which may contribute to cognitive deficits." (PMID 39611170, 2024).
Cognitive impairment (continued). "Thus, microglial Bmal1 may be an important therapeutic target for metabolic and cognitive disorders with relevance to psychiatric disease." (PMID 34050326, 2021). "In this study, we demonstrated that selective ablation of Bmal1 in dopaminergic neurons induces ADHD-like symptoms, including hyperactivity and cognitive deficits, without causing obvious disruption in circadian period in male mice." (PMID 40646562, 2025). "Pre-clinical studies suggest that NR enhances the performance of the clock genes BMAL1 and PER2, ameliorates chronic sleep deprivation-induced cognitive impairment, and may alleviate oxidative stress and mitochondrial impairment in microglia." (PMID 40573093, 2025). "Interestingly, pretreatment with melatonin was found to ameliorate CRSD‐induced cognitive impairment as well as HDAC3 and Bmal1/Clock interruption in this study." (PMID 37721401, 2024).
dilated cardiomyopathy (16 papers, 2015 to 2025). Cardiomyopathy which is characterized by dilation and contractile dysfunction of the left and right ventricles. "In the BMAL1 knockout human embryonic stem cell (hESC) model, BMAL1 deficient hESC-derived cardiomyocytes exhibited typical phenotypes of dilated cardiomyopathy including attenuated contractility, calcium dysregulation, and disorganized myofilaments." (PMID 35996077, 2022). "Especially for BMAL1, the BMAL1 deficient mice showed symptoms of dilated cardiomyopathy, a disorder of left ventricular dilation and contraction." (PMID 35996077, 2022). "Different with the phenotypes of ClockΔ19 mice, loss of Bmal1 gave rise to age-associated dilated cardiomyopathy, as a result of altered titin isoform component, change of MYH gene expression, and disrupted sarcomere structure." (PMID 32277346, 2020). "We show that BMAL1 deficient hESC-derived cardiomyocytes exhibited typical phenotypes of dilated cardiomyopathy including attenuated contractility, calcium dysregulation, and disorganized myofilaments." (PMID 32277346, 2020). "Global Bmal1-deficient mice displayed age-associated dilated cardiomyopathy (DCM), exhibiting left ventricular dilatation and contractile dysfunction." (PMID 32277346, 2020). "It was shown that mice deficient for another core circadian clock gene, Bmal1, exhibited age-dependent dilated cardiomyopathy." (PMID 26348211, 2015). "Circadian rhythms participate in normal cardiac development and disease in vivo: altered circadian biology is associated with cardiac arrhythmias, myocardial infarction, hypertension, and diabetes, and the loss of Bmal1 in myocytes from birth causes dilated cardiomyopathy and metabolic dysfunction." (PMID 38830405, 2024). "In human embryonic stem cell-derived cardiomyocytes, loss of BMAL1 inhibits mitochondrial fission and mitophagy, impairs oxidative metabolism, and leads to disorganized sarcolemmal structure, decreased contractility, and dilated cardiomyopathy." (PMID 34557221, 2021). "Knockout of the BMAL1 gene causes dilated cardiomyopathy in mouse models, and cardiac-specific deletion of BMAL1 initiates diastolic dysfunction, increases fibrotic responses, and impairs resolution of inflammation, thereby reducing survival from cardiomyopathy." (PMID 32662059, 2020). "It is known that deletion of the core circadian gene Bmal1 in mice causes dilated cardiomyopathy." (PMID 32277346, 2020). "Also, a BMAL1 knockout human embryonic stem cell (hESC) model showed that BMAL1 deficient hESC-derived cardiomyocytes exhibited typical phenotypes of dilated cardiomyopathy including attenuated contractility, calcium dysregulation, and disorganized myofilaments." (PMID 35996077, 2022). "Much like the cardiomyocyte-specific Bmal1 knockout, cardiomyocyte-specific Reverbα/β deletions lead to dilated cardiomyopathy and impaired metabolism in the mouse heart, eventually resulting in premature death." (PMID 36062878, 2022). "Genetic deletion of the Bmal1 gene in mouse cardiomyocytes results in dilated cardiomyopathy, decreased heart rate and increased arrhythmias." (PMID 34557221, 2021). "Among the circadian genes permanently reduced by Dox in LV tissue was Bmal1, an interesting feature since Bmal1-KO mice develop age-dependent dilated cardiomyopathy." (PMID 34669013, 2021). "BMAL1 knockout mice had depressed cardiovascular circadian rhythms and developed age-dependent dilated cardiomyopathy." (PMID 32050674, 2020). "Physiological rhythms of heart rate and blood pressure are lost in Bmal1 knockout mice, and such mice developed dilated cardiomyopathy." (PMID 32050674, 2020). "Cardiomyocyte-specific Bmal1-KO mice exhibit dilated cardiomyopathy with prolonged and diminished circadian oscillation of CV function." (PMID 29385702, 2018).
dilated cardiomyopathy (continued). "A cardiomyocyte-specific CLOCK dominant-negative mutant holds some degree of similarity to the cardiomyocyte-specific Bmal1 knockout, including hypertrophy, impaired metabolism, and loss of gene expression rhythmicity, but does not progress to the lethal dilated cardiomyopathy." (PMID 36062878, 2022). "Interestingly, in a BMAL1-knockout mice model, it has been demonstrated that blood pressure decreases by approximately 7 mmHg, that physiological heart rate and blood pressure rhythms are lost, and that dilated cardiomyopathy develops." (PMID 32722512, 2020). "Our data suggested that Bmal1 ablation reduced BNIP3 expression and impaired normal mitochondrial quality control process, which might gradually induced abnormal cardiomyocyte function and phenotypes of dilated cardiomyopathy." (PMID 32277346, 2020).
prostate carcinoma (16 papers, 2019 to 2026). A carcinoma that arises from epithelial cells of the prostate gland. "In particular, CRY1, CRY2, ROR, and BMAL1 have been implicated in the progression of prostate cancer." (PMID 39062777, 2024). "A reduction in the expression of circadian genes, including CLOCK, CRY1, CRY2, PER2, and BMAL1, has been associated with an increased risk of prostate cancer." (PMID 39062777, 2024). "Epidemiological studies of night shift workers provide strong evidence for the association between prostate cancer and gene variants, including BMAL1, NPAS2, CRY2 and PER2." (PMID 36291899, 2022). "Several reports have suggested that BMAL1 can suppress the growth of tumor cells in some cancers, such as prostate cancer, epithelial ovarian cancer, and lymphocytic leukemia." (PMID 32231148, 2020). "It has been reported that BMAL1, a key transcription factor in circadian rhythms, regulates the incidence and maintenance of tumor cells in several types of cancer, such as ovarian cancer, lymphocytic leukemia, and prostate cancer." (PMID 32231148, 2020). "In prostate cancer stem cells, PER3 has been shown to enhance the expression of BMAL1, resulting in the phosphorylation of β-catenin and subsequent activation of the Wnt/β-catenin pathway." (PMID 40690007, 2026). "Regarding prostate cancer (PCan), various clock genes, such as ARNTL, CLOCK, BMAL1, Ck1ε, CRY1, CRY2, Npas2, and PER1-3, are found to be involved in this type of carcinoma." (PMID 38892035, 2024). "Although associations between the circadian clock and the pathogenesis of prostate cancer are elucidated in the basic and clinical literature, the relationships among Bmal1 signaling, BPH and prostate cancer remain for future research to elucidate." (PMID 36232573, 2022).